FAM90A19 (family with sequence similarity 90 member A19)
Synonyms: FAM90A19P; FAM90A18P
Tractability: No criterion of Open Targets' tractability assessment is met for any kind of drug.
Gene: Protein-coding gene on chromosome 8 (7,751,570 to 7,756,692, forward strand). Ensembl gene ENSG00000285657.
Subcellular location (Human Protein Atlas): Nucleoplasm; Nucleoli
Homologues: Orthologues: mouse Fam90a1b (28% identical), mouse Fam90a1a (27% identical), rat Fam90a1l1 (26% identical). Paralogues in human: FAM90A18 (100% identical), FAM90A9 (99% identical), FAM90A16 (99% identical), FAM90A17 (99% identical), FAM90A8 (98% identical), FAM90A10 (98% identical), FAM90A15 (98% identical), FAM90A13 (97% identical), FAM90A14 (97% identical), FAM90A23 (97% identical), FAM90A3 (97% identical), FAM90A5 (97% identical), and 9 more.